IL4 (interleukin 4)
Diseases named in the same sentence as IL4 in open-access papers (continued):
Sharing a sentence is not in itself a finding about the gene and the disease.
endometriosis (continued). "ROC curve analysis revealed the plasma levels of miR-17 was useful biomarker for differentiating women with and without endometriosis, the combination of miR-17, IL-4, and IL-6 could improve the diagnostic power." (PMID 29901577, 2018). "The interleukin IL-4/IFN-γ, IL-10/IFN-γ, and IL-4/IL-2 ratios are higher in women with endometriosis, probably in the late stage." (PMID 40508002, 2025). "The administration of the vaccine before the induction of endometriosis prevented the increase of Th-2 dependent cytokines: IL4, IL6, and IL-10, which is typically observed during the development of endometriosis." (PMID 34945174, 2021). "Women with endometriosis have been observed to have more Th2 lymphocytes as a result of strong intracellular expression of IL-4 and lack of IL-2 in lymphocytes isolated from ectopic lesions." (PMID 37446108, 2023). "Among anti‐inflammatory cytokines, IL‐4, IL‐10, and transforming growth factor‐beta (TGF‐β) levels are also elevated both in the peripheral blood and in the peritoneal fluid of patients with endometriosis." (PMID 37693240, 2023). "IL-4 levels were not significantly different between the non-endometriosis and eutopic groups in the proliferative phase." (PMID 35269619, 2022). "Indeed, in endometriotic lesions, the levels of IFN-γ and IL10 and the ratios of IL4/IFN-γ, IL4/IL2 IL10/IFN-γ, and IL10/IL2 are significantly elevated in the peritoneal fluid of endometriosis patients compared to healthy controls." (PMID 35935991, 2022). "M0s, proinflammatory macrophages [M(LPS+IFN-γ)], prorepair macrophages [M(TGF-β + IL-10 + IL-4)], and macrophages activated with PF from women without endometriosis [M(No Endo)] were included for comparison." (PMID 31291762, 2019). "In patients with endometriosis, the level of miR-23b decreased significantly, the levels of IL-4 and IL-6 increased remarkably compared with that in patients without endometriosis." (PMID 29901577, 2018). "In women with endometriosis, a polarization towards Th2 cells has been observed due to strong intracellular expression of IL-4 and absence of IL-2 from the lymphocytes isolated from the ectopic lesions." (PMID 26247027, 2015). "IL-4 present in human ovarian endometriomas can stimulate the proliferation of endometrial stromal cells, while the CCL5/CCR5 axis may promote endometriosis progression via T-cell suppression and recruitment of CCR5+ myeloid-derived suppressor cells." (PMID 39385609, 2024). "In our study, the analysis of the correlations regarding Ucn1 serum concentrations and cytokines levels including IL-2, IL-4, IL-6, IL-10 and IFN-gamma also brought not so many significant dependencies among women with endometriosis and healthy controls." (PMID 37175494, 2023).
Hepatitis (39 papers, 2008 to 2024). Inflammation of the liver. "IL-4 has been associated with the initiation of drug-induced hepatitis." (PMID 30305319, 2018). "However, both IFN-γ and IL-4 cytokine secretions in conventional T cells are barely detectable, Therefore, reduced severity in Con A-induced hepatitis in the B7-deficient mice correlates to decreased IFN-γ by NKT cells." (PMID 18628995, 2008). "It was demonstrated that ConA-induced hepatitis is moderated by helper T-cells, Kupffer cells, and natural killer T cells, which induce apoptosis of hepatocytes by Fas-FasL interaction and IL-4 release." (PMID 35631676, 2022). "A significant increase in the number of DCs in infected mouse livers, with higher CD86 expression and IL-4, IL-10 and IL-12 secretion, suggested that DCs were involved in S. japonicum infection-induced hepatitis." (PMID 34692568, 2021). "IL-5 was shown to be involved in the maturation and differentiation of eosinophils, and IL-15 can ameliorate hepatitis by inhibiting cytokine production (including IL-4 and IL-5) to reduce the infiltration of hepatic eosinophils." (PMID 33506011, 2021). "In our study, we found high expression of IL-4 in higher grades of hepatitis activity and late stages of fibrosis." (PMID 33906302, 2021). "IL-4 had an immunoregulatory role in immune-mediated drug-induced liver injury; this represents a unique condition where hepatitis can be initiated by drug haptens or self-proteins." (PMID 34422219, 2021). "Two recent studies suggest the importance of iNKT cells and iNKT cell-derived IL-4 in the pathogenesis of Con A-induced hepatitis." (PMID 33175848, 2020). "IL-12, a type I helper T cell cytokine, is involved in pathogenesis of Con A-induced hepatitis by enhancing IL-4 production in iNKT cells." (PMID 33175848, 2020). "Our results demonstrate that peripheral dopamine controlled by gut microbes inhibits IL4 and IFNγ production in iNKT cells and suppresses iNKT cell-mediated hepatitis." (PMID 30386344, 2018). "Covalent modification of JHDN-5 and IL-4 is required for the development of hepatitis in BALB/c mice." (PMID 30305319, 2018). "In summary, we demonstrate that peripheral dopamine controlled by gut microbes inhibits IL4 and IFNγ production in iNKT cells and suppresses iNKT cell-mediated hepatitis." (PMID 30386344, 2018). "In summary, our data show that sorcin−/− animals display enhanced ConA-induced hepatitis and express more cytokines (IL-2, IL-4, IL-17, and IFN-γ) than the wild-type controls, indicating that sorcin acts as a negative regulator in immune response in vivo." (PMID 28706517, 2017). "Intrasplenic transplantation of Ad-IL-18BP/IL-4-BNL.CL12 cells alleviated the severity of inflammation in ConA-induced experimental hepatitis and provides a useful basis for the targeted gene therapy of liver disease." (PMID 23516562, 2013). "The current study has shown in mouse ConA-induced hepatitis that IL-4 gene delivery resulted in anti-inflammatory effects in vivo, reducing liver injury through the inhibition of proinflammatory cytokines." (PMID 23516562, 2013). "We also found that serum levels of IL-18 were significantly downregulated in response to local Ad-IL-18BP/IL-4 treatment in mice with hepatitis." (PMID 23516562, 2013). "Our data show for the first time the marked effect of modifying Th1/Th2 imbalance in ConA-induced hepatitis mice after local Ad-IL-18BP/IL-4 gene therapy." (PMID 23516562, 2013). "Our results strongly suggest that IL-18BP/IL-4 gene transfer can prevent ConA-mediated hepatitis and liver injury." (PMID 23516562, 2013). "It appears that IL-4 can regulate TNFα production in ConA-induced hepatitis, as exogenous IL-4 can boost TNFα levels." (PMID 22347449, 2012). "Interleukin-4, a cytokine with mainly regulatory activity, is also required for the establishment of concanavalin A-induced hepatitis." (PMID 23905033, 2011).
Hepatitis (continued). "Furthermore, the influence of the studied compound on the levels of several other relevant cytokines, such as IL-1β, IL-4, IL-12, and IL-17A, was investigated in mice with ConA-induced hepatitis." (PMID 33919375, 2021). "Reduced hepatitis and CYP2E1 autoantibodies in IL-4-deficient mice, as well as the detection of CYP2E1 IgG4 subclass autoantibodies in patients with anesthetic hepatitis, support a role for IL-4 in the development of CYP2E1 autoantibodies and hepatitis." (PMID 30305319, 2018). "Aithal reported that the frequencies of the variant alleles for IL-10 and IL-4 were significant higher in patients with diclofenac-induced hepatitis compared with both healthy controls and subjects on diclofenac without hepatitis." (PMID 25789467, 2015). "IL-4 therefore has the potential to reduce inflammation in ConA-induced hepatitis." (PMID 23516562, 2013). "IL-4 and IL-18 are considered essential for the development of ConA-induced hepatitis." (PMID 23516562, 2013). "However, in that eczema vaccinatum model, skin NK cells were activated in a IL-4 dependent way, while in Poly I:C-induced hepatitis, hepatic NK cells were activated by Poly I:C directly and the inflammatory cytokines IL-12 and type I IFN." (PMID 24069246, 2013). "This study implied that IL-4 gene therapy might be a useful approach to the reduction of inflammation in hepatitis." (PMID 23516562, 2013). "In addition to IFNγ and IL-4, osteopontin produced by activated NKT also contributes to ConA-induced hepatitis, indicated by the resistance to ConA-induced hepatitis by osteopontin-deficient mice." (PMID 22347449, 2012). "Other research has highlighted the role of inflammatory and/or immunomodulatory interleukins production by NKT cells (especially IFN-γ, IL-4, TNF-α, and IL-10) in the pathogenesis of ConA-induced hepatitis." (PMID 38132174, 2023). "Hepatitis is further aggravated, and HCC is further encouraged by the simultaneous production of TNF-α, IFN-γ, IL-12, IL-4, and IL-13." (PMID 36281288, 2022). "The level of IL-4, IL-17 and CD163 was positively correlated with the grade of hepatitis activity; marked grades of hepatitis activity showed almost the highest degree of expression, and vice versa." (PMID 33906302, 2021). "IL-4 and IFN-γ are important cytokines to mediate murine Con A-induced hepatitis, thus plasma levels of each factor were measured in Con A-treated WT, S1KO, and S1Tg mice." (PMID 33175848, 2020). "Injection of α-Galcer into mice induces iNKT activation, with rapid production of IL-4 but delayed production of IFN-γ, which results in mild hepatitis and liver injury, as we have also observed." (PMID 29541077, 2018). "For example, in a mouse model of hepatitis, the galectin-3 inhibitor attenuated liver damage and proinflammatory T cell-mediated cytokine release (IFN-γ- and IL-17- and IL-4 producing CD4+ T cells)." (PMID 25387690, 2014). "TNF-α, IFN-γ, and IL-4 produced by macrophages, regulatory T cells, and natural killer T (NKT) cells play important roles in the development of the Con A induced hepatitis." (PMID 25126542, 2014). "We therefore examined the influence of intrasplenic transplantation of Ad-IL-18BP/IL-4-BNL.CL2 cells on cytokine expression in peripheral blood and liver in mice with ConA-induced hepatitis." (PMID 23516562, 2013). "We found that Ad-IL-18BP/IL-4 treatment resulted in marked attenuation of Akt, p38 MAPK, NF-κB p65 and JNK1-2 activity in ConA-induced hepatitis." (PMID 23516562, 2013). "Sex bias has been demonstrated previously in concanavalin A immune-mediated hepatitis, in which female BALB/c mice develop more severe hepatitis and exhibit higher levels of plasma TNF-α, IFN-γ, and IL-4 than do males." (PMID 23577207, 2013). "Inflammatory cytokines such as IFNγ, IL-4 and TNFα that are produced by activated NKT cells are essential mediators for induction of hepatitis." (PMID 22347449, 2012).
Hepatitis (continued). "Our study provides a molecular basis for the lack of response to the hepatitis B vaccine, including defective antigen presentation, decreased T cell activity, and reduced IL-4 secretion, as well as novel insight into the role of NKT cells in the immune response to the hepatitis B vaccine." (PMID 37593735, 2023). "Additionally, compound 34 strongly reduced serum concentrations of TNFα, IFNγ, and IL-4, and diminished serum ALT and AST activities in ConA-induced hepatitis in mice." (PMID 35631676, 2022). "The levels of several other inflammatory mediators, i.e., IL-1β, IL-4, IL-10, IL-12, and IL-17A, were measured in the serum of mice with ConA-induced hepatitis in the presence and absence of GRMS-55." (PMID 33919375, 2021). "Treatment with retinoic acid (RA) attenuated Con A-induced hepatitis by directly altering retinoic acid receptor alpha (RAR-α) and mitogen-activated protein kinase- (MAPK-) related signaling molecules, which reduced IFN-γ and IL-4." (PMID 33506011, 2021). "IL-4−/− mice immunized with TFA-JHDN-5 developed significantly less hepatitis and TFA and CYP2E1 autoantibodies than did BALB/c mice, suggesting that IL-4 promotes TFA-JHDN-5-induced hepatitis and antibodies, a finding similar to that in our prior studies." (PMID 30305319, 2018). "TFA-JHDN-5 immunizations induced significantly more hepatitis, serum levels of TFA antibodies, CYP2E1 autoantibodies, and hepatic tissue levels of interleukin (IL)-1β, IL-2, IL-4, IL-5, IL-6, IL-17, interferon (IFN)-γ, and tumor necrosis factor (TNF)-α by 3 weeks." (PMID 30305319, 2018). "Of significance to the present study is that the levels of many cytokines (including IL-18, IFNs, TNF-α, IL-4 and TGF-β1) are elevated during hepatitis progression, and have been demonstrated to exhibit antiviral activity in both transgenic mice and cell culture systems." (PMID 19374779, 2009). "The difference in the proportions of immune cells in S. japonicum- and S. mansoni-induced hepatic granulomas is due to a glycoprotein released by S. mansoni eggs, known as the IL-4-inducing principle of schistosome eggs/α-1, which is not expressed by S. japonicum eggs." (PMID 35335612, 2022). "In both α-GalCer- and Con A-induced murine hepatitis models, CD160−/− mice suffered from severe inflammation with elevated IL-4, IL-6, IFN-γ, and TNF-α and could not fully recover from lethal Con A challenge." (PMID 31332204, 2019).
chronic rhinosinusitis (38 papers, 2009 to 2025). Chronic form of sinusitis. "The pathogenesis of chronic sinusitis is still unclear; however, the nasal cavity and paranasal sinuses are commonly affected by type 2 inflammation, which is caused by Th2 cytokines such as interleukin (IL)-5, IL-4, and IL-13." (PMID 36983684, 2023). "One study characterized expression patterns of several type 2 inflammatory cytokines including IL-4 and found that only patients with chronic rhinosinusitis with polyps and allergic fungal rhinosinusitis demonstrated an increase in IL-4 gene expression." (PMID 34208325, 2021). "It has been proved that Th2 cells bound to IL-4, IL-5 and IL-13 play the main role in the form of chronic sinusitis with polyps." (PMID 34198970, 2021). "In another study that looked at allergic subjects with chronic sinusitis, IL-4 transcripts were found to be high in the ethmoid sinus mucosa and nasal turbinate tissue." (PMID 22262978, 2012). "Examination of nasal secretions from subjects with chronic sinusitis found higher levels of IL-4 protein when compared with controls." (PMID 22262978, 2012). "Increased IL-4 gene expression and IL-4 protein have been found in the upper airways in subjects with chronic sinusitis found as compared with controls." (PMID 22829846, 2012). "Chronic rhinosinusitis with nasal polyps (CRSwNP) is a subtype of chronic rhinosinusitis characterized by persistent eosinophilic inflammation and activation of the type 2 immune pathway, particularly involving interleukins IL-4, IL-5, and IL-13." (PMID 41281095, 2025). "Because ALOX15 expression depends on IL-4 and IL-13, it has been suggested that dupilumab may counter type 2 inflammation in chronic rhinosinusitis in part by suppressing an IL-4/IL-13/ALOX15 M2 macrophage signaling axis." (PMID 38637492, 2024). "Moreover, reduced expression of the inducible isoform of NO synthase (iNO-synthase) caused by some inflammatory cytokines (IL-4, IL-6, and TGF-β) has been found in the sinus mucosa of chronic rhinosinusitis patients." (PMID 31940834, 2020). "As we did not detect any significant differences between the three groups for IL-4, IL-8, GM-CSF, and eotaxin, we conclude that these mediators are not of distinctive function in chronic rhinosinusitis." (PMID 27127525, 2016).
prostate carcinoma (38 papers, 2010 to 2026). A carcinoma that arises from epithelial cells of the prostate gland. "It has been shown that the levels of IL-4 increases post-irradiation in patients with prostate cancer, and has been implicated in radiation-induced fibrosis." (PMID 32707913, 2020). "In prostate cancer, interleukin-4 has been associated with activation of the androgen receptor, increased proliferation and activation of survival pathways such as Akt and NF-κB." (PMID 28553931, 2017). "In keeping with our results that suggest a probable protective effect of the rs2243250 variant against tumor development, it has been reported that in prostate cancer, the IL-4 5′ variant of promoter sequence, rs2243250 decreases IL-4 activity." (PMID 24278120, 2013). "The interplay between IL-4-driven mechanisms and chronic inflammation, a recognized pathogenic factor in prostate cancer, may further compound its tumor-promoting effects." (PMID 40507238, 2025). "For PCa, previous studies reported that IL-1β, IL-4, and IL-16 gene polymorphisms could affect the incidence of prostate cancer." (PMID 36034203, 2022). "In light of this, two small studies have investigated serum IL-4 levels in prostate cancer patients and have suggested that elevated IL-4 may be linked to disease evolution to castrate resistance." (PMID 24213139, 2011). "Reports on prostate cancer are scarce, but Tazaki and colleagues found similar results, with both IL-4 and IFN- γ significantly upregulated in the serum of PCa patients compared to healthy controls." (PMID 40427694, 2025). "Studies have shown that type 2 innate lymphoid cells are enriched in prostate cancer, which produce interleukin (IL)-4 and IL-13, and are known to regulate tumor microenvironment and promote cancer proliferation." (PMID 38889686, 2024). "The surprising discovery is in the prostate cancer group, the concentrations of the inflammatory cytokines IL-4, TNF-α, IL-1β, and IFN-α were significantly lower than those in the healthy control group (all p < 0.05)." (PMID 38833027, 2024). "Co-incubation of mouse prostate cancer cells with T. vaginalis made adipocytes to increase production of IL-4, CCL2, and IL-6, as well as mRNA levels of CCL2, IL-4, and IL-13." (PMID 37125086, 2023). "Co-cultivation of PC3 prostate cancer cells and primary human myoblasts yielded in higher IL-4 and IL-13 serum levels, which induced syncytin-1, annexin V, and CD133 expression in PC3 cancer cells that was further correlated with an enhanced fusion frequency." (PMID 35562905, 2022). "Other studies examining IL-4′s role in prostate cancer suggest that serum IL-4 concentrations are elevated in patients with benign prostatic disease, and IL-10 and IL-4′s pro tumor effects likely reflect their immunosuppressive properties." (PMID 31174326, 2019). "Here we investigate the influence of interleukin-4 on primary epithelial cells from prostate cancer patients." (PMID 28553931, 2017). "Methylation of the IL-4 gene was moderately to highly elevated in prostate cancer cells and increased DNA methylation of GATA3 was observed in androgen negative prostate as compared to androgen positive cells." (PMID 28969068, 2017). "Here, we have undertaken a clinical investigation of the role of two closely related cytokines, IL-4 and IL-13 in prostate cancer." (PMID 24213139, 2011). "By contrast serum IL-4 levels are elevated in patients with benign inflammatory disease compared to prostate cancer patients amenable to radical therapy." (PMID 24213139, 2011). "Together, these data are consistent with distinct roles for IL-4 in early and late stages of prostate cancer." (PMID 24213139, 2011). "Serum levels of IL-4 are raised in patients with castrate resistant prostate cancer, when compared with patients with organ-confined radically treatable disease." (PMID 24213139, 2011).